SMOC1 (SPARC related modular calcium binding 1)
Description:
Plays essential roles in both eye and limb development. Probable regulator of osteoblast differentiation.
Synonyms: OAS
Tractability: Antibody: UniProt places it where antibodies can reach, with high confidence; UniProt predicts a signal peptide or a membrane-spanning region; its Gene Ontology location is reachable by antibodies, with medium confidence. PROTAC: ubiquitination databases record sites on it; its protein half-life has been measured.
Gene: Protein-coding gene on chromosome 14 (69,854,131 to 70,032,366, forward strand). Ensembl gene ENSG00000198732.
Subcellular location: Secreted, extracellular space, extracellular matrix, basement membrane
Subcellular location (Human Protein Atlas): Plasma membrane; Predicted to be secreted
Gene Ontology:
Molecular function: protein binding; extracellular matrix binding; heparin binding; calcium ion binding
Biological process: eye development; limb development; regulation of osteoblast differentiation; extracellular matrix organization
Cellular component: basement membrane
Genetic constraint (gnomAD): Loss-of-function variants: 22 observed, 52.35 expected, observed/expected ratio (o/e) 0.42, 90% interval 0.3 to 0.6. The upper end of that interval is the gene's LOEUF score, 0.6, which puts it in group 2 of 6, group 1 being the genes least tolerant of losing a copy. Missense variants: 506 observed, 572.47 expected, observed/expected ratio (o/e) 0.88, 90% interval 0.82 to 0.95. Synonymous variants: 192 observed, 215.61 expected, observed/expected ratio (o/e) 0.89, 90% interval 0.79 to 1.
Homologues: Orthologues: chimpanzee SMOC1 (99% identical), macaque SMOC1 (98% identical), dog SMOC1 (97% identical), guinea pig SMOC1 (97% identical), rabbit SMOC1 (96% identical), mouse Smoc1 (96% identical), pig SMOC1 (92% identical), rat Smoc1 (91% identical), tropical clawed frog smoc1 (81% identical), zebrafish smoc1 (69% identical), Drosophila melanogaster magu (28% identical), Caenorhabditis elegans smoc-1 (16% identical). Paralogues in human: SMOC2 (55% identical).
Diseases named in the same sentence as SMOC1 in open-access papers:
SMOC1 is named in the same sentence as 94 diseases in open-access papers, as found by Europe PMC text mining. Sharing a sentence is not in itself a finding about the gene and the disease. The quoted sentences say what the papers report.
glioma (10 papers, 2021 to 2025). A benign or malignant brain and spinal cord tumor that arises from glial cells (astrocytes, oligodendrocytes, ependymal cells). "In contrast to gliomas, positive expression of SMOC1 was reportedly associated with recurrence and a poorer prognosis in pancreatic neuroendocrine tumors." (PMID 38429655, 2024). "In another recent study, a series of basement membrane-related genes, including SMOC1, was used to establish a risk prediction model for gliomas." (PMID 38429655, 2024). "The expression of SMOC1 was associated with various functional states in different types of glioma cells." (PMID 34869577, 2021). "A recent study has analyzed the methylation data of the glioma project from the TCGA database and identified 10 glioma grade-associated cytosine-phosphate guanine sites, which targeted four genes, including SMOC1." (PMID 34869577, 2021). "To get a better understanding of the underlying mechanisms of SMOC1 in glioma, we analyzed the correlations between SMOC1 expression and functional state activities across various types of tumors in the CancerSEA database." (PMID 34869577, 2021). "In addition, multiple lines of evidence suggest that SMOC1 is associated with the prognosis of gliomas." (PMID 38429655, 2024). "Interestingly, SMOC1 expression correlated negatively with infiltration by B cells, CD4 + T cells, CD8 + T cells, macrophages and dendritic cells in LGGs, suggesting that SMOC1 may be associated with the tumor microenvironment of glioma." (PMID 38429655, 2024). "Research has also noted a relationship between methylation patterns at CpG sites targeting SMOC1, KCNA4, SLC25A21, and UPP1, and the molecular characteristics of glioma, such as IDH mutations and 1p/19q co‐deletions, which aligns with our findings." (PMID 40781854, 2025). "Among these genes, higher expression of SMOC1 correlated positively with a better prognosis in glioma patients." (PMID 38429655, 2024). "Another in silico study identified a seven-gene signature, including SMOC1, which was positively correlated with 5-years OS of glioma patients (Zhang G.-H." (PMID 34869577, 2021). "In this study, we first systematically analyzed the expression level of SMOC1 and its prognostic value in glioma." (PMID 34869577, 2021). "CpG site of UPP1 demethylate as glioma grade increases while the remaining genes, SMOC1, KCNA4, and SLC25A21, methylate along with higher tumor grade." (PMID 33498463, 2021). "The TIMER database was used to investigate the relationship between immune infiltration and SMOC1 expression in glioma." (PMID 34869577, 2021). "Through the CGGA dataset, we explored the relationship between SMOC1 expression and glioma subtypes, including IDH mutant status, 1p19q codeletion status, recurrent status, and patient's age status." (PMID 34869577, 2021). "The CGGA database was used as an independent database to confirm the prognostic value of SMOC1 in glioma." (PMID 34869577, 2021). "The expressions of SMOC1 in glioma (LGG and GBM) and LUAD were further analyzed in the GEPIA2 database." (PMID 34869577, 2021). "In the further analysis in CancerSEA, we found that the expression of SMOC1 was correlated with several important functional states in glioma cells, especially stemness, hypoxia, EMT, and metastasis." (PMID 34869577, 2021). "Our analyzed data showed a dramatic reduction in SMOC1 expression and we predict the main function of SMOC1 in Grade IV glioma is to promote tumor invasion and migration since rapid spreading is one of the signatures of glioblastoma." (PMID 33498463, 2021). "We found that the expression of SMOC1 was significantly increased in IDH mutant gliomas (p = 3.1e-69), 1p19q co-deletion gliomas (p = 5.6e-38), primary gliomas (p = 0.00074), and the age< 42 group (p = 5.1e-07)." (PMID 34869577, 2021). "Smoc1 can attenuate the migration effect of tenascin‐C on U87 glioma cells." (PMID 36560848, 2023).
glioma (continued). "Also, the Cancer Single-Cell State Atlas database was used to evaluate the correlation between SMOC1 expression and functional state activities in glioma cells." (PMID 34869577, 2021). "In U87 glioma cells, SMOC1 inhibits the tenascin-c-induced chemo-attractive effect." (PMID 34869577, 2021). "In addition, we found that the expression of SMOC1 was significantly increased in subtypes of glioma through the CGGA dataset." (PMID 34869577, 2021). "In high-grade glioma, SMOC1 was significantly positively correlated with stemness (correlation = 0.42, p < 0.001) and negatively associated with hypoxia (correlation = -0.39, p < 0.001), EMT (correlation = -0.38, p < 0.001), and metastasis (correlation = -0.32, p < 0.001)." (PMID 34869577, 2021). "Therefore, we further analyzed the expression of SMOC1 in glioma and LUAD via the GEPIA2 and CGGA databases." (PMID 34869577, 2021). "Together with the functional analysis, our findings strongly suggest that SMOC1 might play an important role in the tumor microenvironment of glioma, thereby influencing glioma development and progression." (PMID 34869577, 2021). "However, the functional role and underlying mechanism of SMOC1, HIPK2, UBA52, S100A6, PPP1CB, CALD1, and TMSB4X in the occurrence and development of diffuse high-grade gliomas was still unknown." (PMID 39530009, 2024). "Differentially expressed genes (DEGs) in the glioma samples relative to normal samples were screened from the GEO database, and five prognostically relevant BM-related genes, including NELL2, UNC5A, TNC, CSPG4, and SMOC1, were selected using Cox regression analyses for the risk score model." (PMID 36292695, 2022). "Also, SMOC1 has even been identified as a new cancer-related protein by interacting with tenascin-c, and it inhibits the tenascin-c induced chemo-attractive effect in U87 glioma cells." (PMID 34869577, 2021). "In comparison to normal tissue, spatial enrichment for SMOC1, ACAN, and SEMA6A transcripts was evident in cells of grade 2 glioma samples." (PMID 41366031, 2025). "In contrast, key regulators of OPC specification and maintenance, including MYT1, OLIG2, PDGFRA, PTPRZ1, SMOC1, and SOX8 were hypomethylated in PM gliomas." (PMID 37055795, 2023). "Quantitative PCR and immunohistochemical analysis showed that LIF, LOX, MMP9, S100A4, SRPX2, and TIMP1 were expressed at high levels in glioma, whereas SLITI1 and SMOC1 were expressed at low levels, consistent with our previous results." (PMID 36560848, 2023). "The findings explored the prognostic value of SMOC1 in low-grade glioma (LGG) and provided new ideas for exploring the potential mechanism of SMOC1 in glioma development and progression." (PMID 34869577, 2021). "Gene expression of SMOC1, KCNA4, and SLC2521 declined as patient glioma grade increased while UPP1 gene expression showed a positive relationship with tumor grade." (PMID 33498463, 2021). "However, the prognostic value of SMOC1 in glioma needs to be validated in clinic samples, and as little was known about the biological function of SMOC1 in tumor genesis and progression, further in vitro and in vivo investigations are required to clarify the role of SMOC1 in glioma." (PMID 34869577, 2021). "In gliomas, SMOC1, S100A6, CTSB, SPP1, and IGFBP2 serve as a potential therapeutic target in glioma." (PMID 39530009, 2024). "SMOC1 was first discovered in 2002, is widely distributed in the basement membrane ECM of many tissues, and is known to be upregulated in oligodendrocytoma and astrocytic tumors and can inhibit the migration of glioma U87 cells induced by tenascin C." (PMID 36686480, 2022). "Moreover, the expression of SMOC1 was correlated with stemness, hypoxia, EMT, and metastasis of glioma cells." (PMID 34869577, 2021). "However, the specific relationship between the expression level of SMOC1 and the prognosis of glioma patients has not been evaluated yet." (PMID 34869577, 2021).
glioma (continued). "Compared with IDH-wild-type, 1p19q non-codeletion, and recurrent subtypes, the expression of SMOC1 was increased in IDH mutant, 1p19q co-deletion, and primary gliomas." (PMID 34869577, 2021). "Consistent with the analysis of the TCGA datasets in GEPIA2, the survival analysis of CGGA datasets also showed a significant positive correlation between SMOC1 expression and better prognosis in all WHO grade I, WHO grade II, and WHO grade III gliomas but not in WHO grade IV glioma." (PMID 34869577, 2021).
Alzheimer disease (9 papers, 2021 to 2025). A progressive, neurodegenerative disease characterized by loss of function and death of nerve cells in several areas of the brain leading to loss of cognitive function such as memory and language. "Recent studies demonstrated that SMOC1 was also associated with Alzheimer's disease." (PMID 34631806, 2021). "Recently, WNT9A and SMOC1 were proposed as biomarkers of dementia and Alzheimer's disease, respectively." (PMID 39812213, 2025). "SPARC-related modular calcium-binding protein 1 (SMOC1) has been shown to be one of the most dysregulated proteins in Alzheimer’s disease (AD) brain tissue, cerebrospinal fluid (CSF), and plasma in 23 proteomic analyses to date." (PMID 39585417, 2024). "SMOC1 has emerged as one of the most significant and consistent new biomarkers of early Alzheimer’s disease (AD)." (PMID 39574902, 2024). "SMOC-1 was found to be elevated in asymptomatic Alzheimer’s disease (AD) patient cortex as well as being enriched in amyloid plaques and in AD patientcerebrospinal fluid, arguing for SMOC-1 as a promising biomarker for AD." (PMID 39291144, 2023). "The established Alzheimer's disease associated proteins SMOC1 and CHI3L1, as well as other remaining top DEPs were not part of a functionally annotated cluster." (PMID 40491829, 2025). "The two top overlapping DEPs, SMOC1 and CHI3L1, also showed a consistent upregulation in Alzheimer's disease." (PMID 40491829, 2025). "Two DEPs, ‘SPARC-related modular calcium-binding protein 1’ (SMOC1) and ‘chitinase-3 like-protein-1’ (CHI3L1, also known as YKL-40), both well-established markers of Alzheimer's disease, were found across 14 studies constituting the highest overlap among all studies." (PMID 40491829, 2025).
amyloid (7 papers, 2024 to 2025). "Consistently with previous findings, SMOC1 was enriched in both vascular and parenchymal amyloid deposits, showing clear co-localization with ThioS-positive CAA and the dense cores of plaques, suggesting a broader amyloid affinity." (PMID 41282800, 2025). "Despite significantly different total amyloid plaque loads in the temporal cortex and hippocampus (p < 0.0001), a similar degree of SMOC1 colocalization with amyloid plaques was observed (43.8 ± 2.4% and 46.9 ± 6.8% respectively, p = 0.962)." (PMID 39574902, 2024). "Notably, key ECM-associated proteins such as SMOC1, MDK, and SFRP1 are recurrently elevated and exhibit strong specificity to amyloid pathology, spanning both parenchymal plaques and vascular amyloid in CAA." (PMID 41282800, 2025). "Interestingly, SMOC1 also colocalized with a similar subpopulation (27.2 ± 9.0%) of the small number of amyloid plaques present in control cases (amyloid load: 0.003 ± 0.001%)." (PMID 39574902, 2024). "In addition, SMOC1 with the abundant expression in both parenchymal plaques and CAA, has emerged as an important biomarker of amyloid deposition in the brain." (PMID 38713744, 2024). "Given the variation observed in amyloid plaque load in our cohort, particularly in AD, we next evaluated SMOC1 colocalization in amyloid plaques independent of disease stage." (PMID 39574902, 2024).
breast carcinoma (7 papers, 2014 to 2023). "The expression of SMOC1 was significantly correlated with the survival of six cancer types, including brain glioma, colorectal cancer, eye uveal melanoma, breast cancer, LUAD, and ovarian cancer." (PMID 34869577, 2021). "Compared with low SMOC1 expression, high expression level of SMOC1 was correlated with better prognosis in brain glioma [overall survival (OS), HR = 0.55, 95% CIs, 0.4–0.75, Cox p-value = 0.0001], breast cancer, and ovarian cancer." (PMID 34869577, 2021). "SMOC1 plays essential roles in both eye and limb development, whereas GOLM2’s function is not well characterized but was associated with breast cancer and glioblastoma." (PMID 37047248, 2023). "Nevertheless, the relationships among VPS28, SMOC1, and breast cancer are not currently known, and thus, further investigation in BC patients is required." (PMID 32964046, 2020). "SMOC1 is SPARC (secreted protein, acidic and rich in cysteine) related modular calcium binding 1 and has been found a correlation with malignant progression, such as brain tumor, colorectal cancer and breast cancer." (PMID 25436889, 2014). "However, the function of SMOC1 in breast cancer remains unknown, and SMOC1 methylation has not been reported in other tumor types." (PMID 29435136, 2018).
coloboma (7 papers, 2011 to 2023). An abnormality in which a part of a structure in one or both eyes is missing. "SMOC proteins are localized to BMs in various developmental contexts, and SMOC1 has been suggested as a fusion-specific BM-modulating factor due to causative mutations identified in patients and animal models with colobomas." (PMID 33505973, 2020). "Indeed, variants in GDF6 (BMP13), BMP4, and SMOC1 are linked to inferior coloboma and microphthalmia." (PMID 29522511, 2018). "We will also screen a cohort of human patients to determine if hypomorphic mutations in SMOC1 may cause coloboma." (PMID 21750680, 2011). "These included the known human coloboma associated genes (indicated by #): SMOC1, PAX2, VAX1 and ALDH6, in addition to the coloboma candidates from other animal studies CHRDL1 and CYP1B1 (indicated by •)." (PMID 31162046, 2019). "Among these were the known human MAC genes TENM3, SMOC1, PAX2, ALDH1A3, and BMPR1B, in addition to NID1, VAX1, and NTN1, which have been previously identified as MAC or coloboma candidates based on animal studies." (PMID 36830662, 2023).
brain tumors (6 papers, 2014 to 2025). "Increased SMOC1 expression is detected in brain tumors and particularly in LGG, correlating with improved survival." (PMID 40781854, 2025). "In brain tumors, SMOC1 interacts with tenascin-C, an extracellular matrix protein overexpressed in various tumor types." (PMID 38429655, 2024). "The expression of SMOC1 was increased in some brain tumors, such as oligodendroglioma and astrocytic tumors." (PMID 34869577, 2021). "SMOC1, a SPARC-related ligand overexpressed in brain tumors, recovered BST2, IGSF23, and SMOC2 as the highest-ranking hits." (PMID 36178190, 2022).
Cognitive impairment (6 papers, 2018 to 2024). Abnormal cognition is characterized by deficits in thinking, reasoning, or remembering. "Across all cognitively unimpaired (CU) individuals and patients with mild cognitive impairment (MCI), SMOC1 and ITGAM showed the strongest positive associations with global Aβ-PET levels, all associations being independent of tau-PET levels." (PMID 39187705, 2024). "Assessing the whole sample and the subgroup of subjects with cognitive impairment, we could decipher the strong contribution of some CSF proteins, such as SMOC1 and 1433Z." (PMID 30021611, 2018). "The distribution of SMOC1 in human brain tissue was assessed in 3 brain regions (temporal cortex, hippocampus, frontal cortex) using immunohistochemistry in a cohort of 73 cases encompassing advanced AD, mild cognitive impairment (MCI), preclinical AD and cognitively normal controls." (PMID 39574902, 2024). "The distribution of SMOC1 in human brain tissue was assessed in 3 brain regions (temporal cortex, hippocampus, and frontal cortex) using immunohistochemistry in a cohort of 73 cases encompassing advanced AD, mild cognitive impairment (MCI), preclinical AD, and cognitively normal controls." (PMID 39585417, 2024). "SMOC1, YWHAZ, ALDOA and MAP1B emerged as biomarker candidates that could best discriminate between individuals with AD and non-AD cognitive impairment as well as Tau/β-amyloid ratio." (PMID 32514259, 2020). "Namely, SMOC1, ALDOA, MAP1B and YWHAZ proteins emerged as biomarker candidates with low coefficients of variation that could best discriminate AD from non-AD cases with cognitive impairment as well as predict individuals with high Tau/Aβ ratio in CSF." (PMID 32514259, 2020).
microphthalmia (6 papers, 2011 to 2023). Congenital or developmental anomaly in which the eyeballs are abnormally small. "Interestingly, genes involved in microphthalmia (VAX1, ALDH1A3, GJA1, and SMOC1) and retinal dystrophies (ADAMTS9, KCNJ13, CA2 and ABCA4) were also selected." (PMID 37479765, 2023). "This gene has previously been associated with anophthalmia and microphthalmia but not to inner ear function, except by the report generated by IMPC that heterozygous mice carrying SMOC1 mutations display abnormal ABR recordings." (PMID 34784928, 2021).
colorectal cancer (4 papers, 2014 to 2024). A primary or metastatic malignant neoplasm that affects the colon or rectum. "However, high expression of SMOC1 was associated with poor prognosis in colorectal cancer and LUAD." (PMID 34869577, 2021). "We previously reported that the CpG island of SMOC1 is frequently methylated in traditional serrated adenomas (TSAs) and colorectal cancers (CRCs) but is rarely methylated in sessile serrated lesions (SSLs)." (PMID 38429655, 2024). "Besides, another study suggests that the aberrant expression of SMOC1 can inhibit the proliferation and colony formation in colorectal cancer cells, as well as tumor formation in vivo." (PMID 34869577, 2021).
glioblastoma (4 papers, 2021 to 2024). The most malignant astrocytic tumor (WHO grade IV). "SMOC1 was overexpressed in brain cancer, including oligodendrogliomas, astrocytomas, and glioblastomas." (PMID 33828913, 2021).